MUC1 (mucin 1, cell surface associated)
Diseases named in the same sentence as MUC1 in open-access papers (continued):
Sharing a sentence is not in itself a finding about the gene and the disease.
cancer (continued). "Cancer-related genes MUC1, FN1, and S100-family members were the most clinically relevant in CPTC, while APLN and IL16, both immune-related, were clinically relevant in FVPTC." (PMID 31443155, 2019). "By increasing the association between β-catenin and the MUC1 cytoplasmic tail, ECM1 regulated the EMT progression and cancer stem cell proliferation." (PMID 31335317, 2019). "The goal of this bispecific aptamer is to engage CD16-positive immunocytes with MUC1-positive cancer cells in order to selectively enhance the antitumor cytotoxicity." (PMID 30699986, 2019). "A novel curcumin-loaded magnetic nanoparticle was shown to have potent cancer prevention activity against PDAC through the depletion of collagen 1 and cell surface-associated mucin 1 (MUC1)." (PMID 30665410, 2019). "Our results indicate that, with minimal toxicity, the combination of TAB004 + Lip-MSA-IL-2 was associated with improved survival in the orthotopic murine model of PDA, as well as a lower cancer burden in the PDA.MUC1 mouse spontaneous model of PDA." (PMID 31114758, 2019). "Other research, comparing different subtypes of CCs, confirmed that the most abundantly represented mucins in these cancers were MUC1 (~66%) and MUC5AC (~61%), followed by MUC2 (~24%) and MUC6 (~14%)." (PMID 30875782, 2019). "The first mucin to be characterized structurally was MUC1 and has since been largely studied for its aberrant expression and role in cancer." (PMID 31069176, 2019). "A well-known cancer biomarker, MUC1, is expressed at 8.98-fold higher in exosomes than total cellular membrane proteins." (PMID 30646616, 2019). "Gatipotuzumab has been designed to recognize such a cancer specific, conformational carbohydrate epitope on MUC1 with exceptional high specificity and affinity." (PMID 30642093, 2019). "The National Cancer Institute Project for the Acceleration of Translational Research ranked MUC1 as the second-most promising cancer antigen among 75 candidates." (PMID 31399552, 2019). "MUC1, MUC2, MUC4, and MUC16 are mucins associated with cancer progression, whereas MUC16 is also used for cancer diagnostics." (PMID 31552050, 2019). "Dysregulated and inappropriately glycosylated MUC1 has been correlated with many chronic epithelial diseases and cancers, suggesting when the general function of this glycoprotein is perturbed, normal homeostasis of tissue, cannot be properly maintained." (PMID 31069176, 2019). "We previously published that many patients with those premalignant conditions, similar to many cancer patients, mount a specific anti-MUC1 antibody response." (PMID 31275327, 2019). "PANVAC is a cancer vaccine therapy delivered through two viral vectors, which include transgenes for MUC-1, CEA, and for three human T cell costimulatory molecules." (PMID 31665051, 2019). "Specifically, the 1q21 locus has been correlated with cancer progression along with MUC1 upregulation, further contributing to the proposed role MUC1 has in aggressive PTC phenotype." (PMID 31443155, 2019). "Many monoclonal antibodies (mAbs) specific for MUC1 were developed and some of them resulted from immunisation with carcinoma cells and screening for the binding to carcinoma cells." (PMID 31719620, 2019). "MUC1 is expressed by almost all epithelia, by carcinomas, and (at low levels) by other types of cells, and the extent and the profile of glycosylation is likely to be unique to the particular type of cell." (PMID 31719620, 2019). "Mucin 1 (MUC1) is a heterodimeric protein that is aberrantly overexpressed by diverse types of carcinomas, including those of the breast and lung." (PMID 31399552, 2019). "Astonishingly, in 1999 it was estimated that cancers with aberrant MUC1 expression accounted for 72% of new cases and 66% of deaths in all cancers." (PMID 30450094, 2018). "Specifically, AR20.5 was generated using cancer-specific MUC1 glycoprotein as the immunogen, whereas that for SM3 is a “striped” MUC1 protein." (PMID 29857542, 2018).
cancer (continued). "MUC1 is an oncogene in cancer cells while in normal cells plays a role to protect gastric epithelial cells from pathogens that initiate inflammation and carcinogenesis." (PMID 30212456, 2018). "MUC1 has recently become an interesting target in cancer immunotherapy because of the overexpression of aberrantly glycosylated MUC1 in most solid tumors and several hematological malignancies." (PMID 30031396, 2018). "In this study, the UCNPs conjugated with anti-MUC1 (episialin) are used for the targeted binding of anti-MUC1 with Episialin (MUC1) present on the surface of the cancer cells." (PMID 29783654, 2018). "In this experiment, gold-promoted reduction of silver ions induced voltage changes that, when read through electrochemical stripping analysis, were indicative of MUC1 expression levels, and thus potentially of cancer detection." (PMID 29301363, 2018). "Analysis among the downregulated genes revealed a direct interaction within GALNT1, C1GALT1C1 and MUC1, a protein that carries the Tn antigen, which is present in most of the cancers, including uterine cervical cancer cells." (PMID 30038662, 2018). "Because of its ubiquity and high expression in cancer, MUC1 is an excellent target for multiple cancers." (PMID 29301363, 2018). "Taken together, the results indicate that L2A5 mAb recognizes the STn-antigen in membrane extracts of STn-expressing cancer cells, as well as on STn carrier proteins such as MUC1." (PMID 30111774, 2018). "In early years anti-MUC1 antibodies were conjugated to radioisotopes and used for both imaging and therapy of cancer." (PMID 29857542, 2018). "In this study, we generated Muc1 bispecific antibody Muc1-Bi and tested its function for Muc1 overexpression cancer therapy." (PMID 29357376, 2018). "A high affinity antibody 16A was produced by immunizing mice with MUC1-transfected mutant cancer cells and showed significant glycopeptide binding preference and recognized RPAPGS(GalNac)TAPPAHG epitope." (PMID 29857542, 2018). "As for aptamer-guided multimodal imaging, optical-MR-PET imaging techniques were investigated with anti-MUC-1 aptamers, which showed high cancer-specific detection." (PMID 30029472, 2018). "In this regards, several anti-MUC1 antibodies exhibited excellent internalization while binding to the antigens on the cancer cell surface, which represent promising repertoire of antibodies to be developed as ADC candidates." (PMID 29857542, 2018). "Mucin 1 (MUC1) is a cell membrane glycoprotein overexpressed in many human cancers, including NSCLC." (PMID 30479696, 2018). "Dox was also intercalated into DNA aptamer MA3 that targeted MUC1, which is overexpressed on the surfaces of various cancer cells." (PMID 29617327, 2018). "Based on immunostaining and confocal image analyses, the anti-hMUC1 antibody initially bound to the cell membrane then was internalized in cancer cells that express MUC1." (PMID 29987260, 2018). "L2A5 mAb also showed reactivity to membrane extracts from STn+ cancer cells and purified MUC1 decorated with STn." (PMID 30111774, 2018). "MUC1 has been reported to be an important molecule in many research areas including different cancers, immunity, and immunotherapy." (PMID 30459171, 2018). "Mucin 1 (MUC1) is a heterodimeric protein that is aberrantly expressed in cancer cells, including AML blasts." (PMID 29761849, 2018). "Earlier studies reported Gal-3 interaction with different mucins, including the ocular cell surface MUC, MUC1 and -16, in a galactose-dependent manner or to cancer mucins from human colon cancer cell lines." (PMID 29401627, 2018). "The widespread occurrence of MUC1 across multiple types of cancer has made it a popular immunotherapy target with 16 new trials initiated in 2017 alone." (PMID 30450094, 2018). "MUC1 was reported to not only allow the cancer cells to escape the immune system but also promote cancer cell migration by activating some membrane receptors." (PMID 29854028, 2018).
cancer (continued). "Many TAA have been used as targets for cancer vaccines including Mucin 1 (MUC1), MAGE, NY-ESO-1, Her-2/neu and others." (PMID 30200528, 2018). "The MVA-based cancer vaccine TG4010 targeting the MUC1 antigen has been tested in a phase II trial for renal cell carcinoma (37 patients, metastatic) combined with IFNα2a and IL-2." (PMID 30254636, 2018). "Currently, there is renewed interest in attempting to recruit the host immune system to eliminate cancers, and within this renewed activity, MUC1 continues to arouse interest." (PMID 29784646, 2018). "In the US, it was estimated that 900 000 cancers, out of 1 400 000, harbor overexpression of MUC1 highlighting its attractiveness as a therapeutic target." (PMID 30236127, 2018). "In a 2009 National Cancer Institute pilot project prioritizing 75 cancer antigens, MUC1 was ranked second as an immunotherapeutic cancer vaccine target antigen." (PMID 30200528, 2018). "Cancer vaccines based on MUC1 glycans, with Theratope as the well-known example, have been extensively studied and tested in cancer patients." (PMID 29857542, 2018). "Glycoproteins that carry large amounts of O-GalNAc glycans, such as MUC1 are often overexpressed in cancer and contribute to the bulk of the glycocalyx facilitating integrin clustering that enhances interactions with ligands." (PMID 29903935, 2018). "The use of MUC1 peptide vaccines in human cancer patients has been demonstrated to generate both anti-MUC1 antibody and cytotoxic T-lymphocyte responses." (PMID 30479696, 2018). "Although much of the work relating to MUC1 as a therapeutic target in cancer has focused on the EC domain, interest in the smaller membrane spanning component (MUC1-C) has increased." (PMID 29784646, 2018). "In contrast to low-level luminal or apical expression of the heavily glycosylated MUC1 on normal colonic epithelial cells, cancer cells express high levels of the hypoglycosylated form of MUC1." (PMID 29385680, 2018). "MUC1 is widely overexpressed in various cancers, including hematological malignancies, often in abnormal hypoglycosylated forms with exposed T cell epitope." (PMID 29415891, 2018). "Information relating to the importance of the change in glycosylation of MUC1 and the interaction of specific cancer MUC1 glycoforms with cells in the microenvironment are also suggesting novel approaches." (PMID 29784646, 2018). "The Muc1-Bi bispecific antibody can recruit NK cells to drive potent cancer cell killing in Muc1-overexpression cancer cells, providing a valid alternative for cancer therapy." (PMID 29357376, 2018). "As MUC1 is highly expressed on the cancer plasma membrane, the cancer specificity of an anti-MUC1 DNA aptamer conjugated with QDs was evaluated in A549 cells." (PMID 30029472, 2018). "Target cancer cells were effectively treated with MUC1 aptamer origami-Dox-AuNR (MDOA) because of the synergistic effect of chemo-thermal therapy." (PMID 29617327, 2018). "Previous clinical trials for MUC1-based cancer vaccines have been based on separated sugar and peptide portions." (PMID 29857542, 2018). "This is in addition to the role of MUC1 in cancer progression, invasion, metastasis, angiogenesis, and chemoresistance." (PMID 30031396, 2018). "We observed a statistically significant positive correlation between MUC1 expression and survival in patients with squamous tumors according to the Spearman correlation test (P = 0.020 for carcinoma score and P = 0.008 for dysplasia score)." (PMID 30479696, 2018). "In a Phase I trial (NCT01222624), 74 patients with advanced MUC1-positive carcinomas received PankoMab-GEX intravenously in a three-plus-three dose-escalation design until disease progression." (PMID 29784646, 2018). "These antibodies were used to clone the MUC1 gene and differences in the reactivity of some antibodies with normal epithelia and carcinomas were observed." (PMID 29784646, 2018).
cancer (continued). "• The dominant glycoform of MUC1 expressed by most carcinomas is MUC1-ST, which is expressed on the cell surface and can be secreted." (PMID 29784646, 2018). "Based on these findings, several phase I and II clinical trials have been launched using recombinant viral and TRICOM-based vaccines targeting PSA, CEA, and mucin-1 (MUC-1) in various cancer settings." (PMID 28134800, 2017). "Our data implicate that EGFR inhibitors in addition to combination with PTX can be used to overcome acquired chemotherapy resistance in MUC1-positive cancer." (PMID 28796259, 2017). "In progression to cancer, MUC1 protein expression generally increases, alters location and is coupled with aberrant glycosylation." (PMID 28212575, 2017). "MUC1 (mucin 1) is a heterodimeric glycoprotein expressed on the apical surface of normal epithelium and is overexpressed in diverse cancers." (PMID 28153010, 2017). "EGFR is associated in epithelial cells with the heavily glycosylated transmembrane mucin protein MUC1, a natural ligand of galectin-3 that is overexpressed in cancer." (PMID 28731466, 2017). "MUC1 is a transmembrane heterodimeric oncoprotein that is highly expressed in various cancers and correlates with potential for malignancy." (PMID 28241424, 2017). "Mannan conjugated to MUC1 cancer protein induces immune responses in mice and protects mice against tumor challenge." (PMID 28686222, 2017). "MUC1, the most studied mucin that is involved in the pathogenesis of the multiple cancer types, serves as a scaffold, a signaling adaptor, a transcriptional co-activator, and a metabolic and immune regulator." (PMID 28978023, 2017). "MUC1 is known as an oncogene with anti-apoptotic function in cancer cells; however, in normal gastric mucosa, it is believed that this protein has a role in protecting gastric epithelial cells from attacks that cause inflammation and carcinogenesis." (PMID 28512631, 2017). "Consistent with this notion is our data showing that EGFR was activated by MUC1 in PTX-resistant cancer cells and more importantly, MUC1 inhibition resulted in diminished activity of EGFR and reduced expression of ABCB1 leading to reversal of PTX resistance." (PMID 28796259, 2017). "Overexpression of MUC1 in human cancers blocks the induction of apoptosis and necrosis in response to DNA damaging agents, reactive oxygen species and hypoxia." (PMID 28153010, 2017). "These genes, such as PRKAA1, PLCE1 and MUC1, also play an important role in cancer progression and tumorigenesis." (PMID 27821817, 2017). "The results not only uncover a novel mechanism of MUC1-induced chemoresistance but also implicate ABCB1 as a potential therapeutic target in cancer cells." (PMID 28796259, 2017). "We tested this possibility by fusing two polypeptides consisting in repeated units of two known cancer epitopes (EGFRvIII and MUC1) to the C terminus of Nm-fHbp, Nm-fHbpDomA and NHBA." (PMID 28483926, 2017). "We next examined the role of MUC1 in modulation of cancer cell response to therapy by monitoring MUC1 expression in HeLa229 parental cells treated with PTX." (PMID 28796259, 2017). "The changes in the glycan moieties contribute to the enhanced immunogenicity of MUC1 by exposing the core protein to the humoral response and by modifying the interaction of cancer cells with APC." (PMID 28679396, 2017). "Further, metabolomics profiling identified metabolite alterations in which MUC1 expression modulates cancer cell metabolism to facilitate growth properties of TNBC cells." (PMID 28464016, 2017). "Theratope (STn-KLH) is a therapeutic cancer vaccine that consists of a synthetic antigen including MUC1." (PMID 28085094, 2017). "Treatment of cancer cells with chemotherapy drugs induces the expression of MUC1, which stimulates the activation and nuclear distribution of EGFR." (PMID 28796259, 2017).
cancer (continued). "Since the glycosylation structure of MUC1 changes during the transformation of normal to cancer cells (forming tMUC1), the elimination and equilibrium phases explain the presence of tMUC1 even in healthy individuals." (PMID 28680538, 2017). "Considering that EGFRvIII and MUC1 peptides are promising candidates for cancer therapy, our results pave the way to test the ability of engineered bacteria and OMVs to elicit anti-EGFRvIII and anti-MUC1 specific immune responses." (PMID 28483926, 2017). "Of particular interest was the finding that the expression of MUC1 was considerably upregulated in cancer cells that had acquired chemoresistance following long-term PTX treatment." (PMID 28796259, 2017). "This mucin glycoprotein, MUC-1 or CD227, has been found to be a target for cytotoxic T lymphocytes, and possibly for immunotherapy, hence its use in a possible cancer vaccine." (PMID 28970834, 2017). "This work was translated into human phase I, II and pilot III clinical trials; mannan-MUC1 induces protection against cancer recurrence at 18 years follow-up." (PMID 28686222, 2017). "It is noteworthy that MUC1 was ranked second out of 75 in a priority ranking of cancer antigens from the National Cancer Institute." (PMID 28116088, 2017). "Functional characterization of MUC1 in these two cancers demonstrates that MUC1 mediates the development of acquired chemoresistance of cancer cells." (PMID 28796259, 2017). "MUC1, despite low methylation in normal tissues, demonstrates even lower methylation status across multiple cancers." (PMID 28978023, 2017). "In contrast, WFA-sialylated MUC1 was superior to CA19-9 only for moderately differentiated carcinoma." (PMID 27358229, 2017). "It shows how MUC1 expression is maintained by glandular cells throughout the metaplasia-dysplasia-carcinoma sequence, binding only the epithelial layer in early disease." (PMID 28212575, 2017). "For stage II and IV carcinomas, WFA-sialylated MUC1 showed significantly better diagnostic sensitivity than CA19-9." (PMID 27358229, 2017). "When the results of bile samples were compared with those of serum samples, biliary WFA-sialylated MUC1 and CA19-9 showed similar diagnostic sensitivity in stage I and II carcinomas." (PMID 27358229, 2017). "Confocal microscopy and flow cytometry demonstrated that Apt-Td selectively delivered Dox into the MUC1-positive cancer cells." (PMID 27203221, 2016). "We stained a panel of cancer cell lines with each of the human anti-MUC1 antibodies followed by a dye-conjugated secondary antibody recognizing human IgG Fc." (PMID 27545199, 2016). "Mucin 1 (MUC1) is an important molecular target for cancer treatment because it is overexpressed in most adenocarcinomas." (PMID 27203221, 2016). "MUC1, an oncoprotein that has been shown to be elevated in many cancer types including the lung, also is elevated in macrophages." (PMID 27276704, 2016). "By associating with CIN85, an adaptor protein previously reported to be involved in cell migration, MUC1 confers an invasive property to cancer cells." (PMID 27754373, 2016). "Two component fully synthetic MUC1 glycopeptide cancer vaccines have been synthesized by conjugating MUC1-VNTR including different TACAs either to various T helper epitope peptides, ovalbumin, or different TLR agonists." (PMID 27472370, 2016). "This structural difference in MUC1 between normal and cancerous tissues makes it an attractive target for cancer immunotherapy." (PMID 27472370, 2016). "Other evidence exists confirming the role of hypoglycosylated MUC1 in aberrant signaling in cancer cells." (PMID 27754373, 2016). "In this study, we attempted to construct the first aptamer-tetrahedron complex (Apt-Td) for the targeted delivery of doxorubicin to MUC1-positive cancer cells." (PMID 27203221, 2016). "Dox-loaded Apt-Td also induced a significantly higher cytotoxicity to the MUC1-positive cancer cells versus the MUC1-negative control cells in vitro (p<0.01)." (PMID 27203221, 2016).